BRCA2 (BRCA2 DNA repair associated)
Diseases named in the same sentence as BRCA2 in open-access papers (continued):
Sharing a sentence is not in itself a finding about the gene and the disease.
tumor (continued). "Tumours within the simple-profile subgroup appear similar to the BRCA1 and BRCA2 subgroups in terms of altered segment lengths but differ in that they display considerably less complex genomes." (PMID 19589159, 2009). "Tumour genomes within the BRCA1- and BRCA2-related subgroups were characterised by relatively long stretches of genomic alterations, deletions and copy gains along with occasional high-level amplifications." (PMID 19589159, 2009). "The combined analysis of genomic alterations and tumour phenotypes, presented here, show that BRCA1- and BRCA2-related tumours develop largely through different genetic pathways in terms of the regions altered, while also displaying distinct phenotypes." (PMID 19589159, 2009). "The purpose was to examine the resulting tumour subgroups in terms of their prevalence for BRCA1 and BRCA2 abnormalities." (PMID 19589159, 2009). "We previously showed that tumours of BRCA1 and BRCA2 carriers aged 50 years or older differ significantly from those of younger patients." (PMID 18275599, 2008). "This adds to the mounting evidence suggesting differences in molecular mechanisms involved in normal function and tumor formation in BRCA1 and BRCA2 carriers." (PMID 18542066, 2008). "Among these genes, the recently identified tumor-suppressor genes BRCA1 and BRCA2 contribute to a substantial portion of inherited BCa." (PMID 17915011, 2007). "The oncogenes c-myc, c-met, k-ras and the neoplastic progression protein-3 (Npn3) were also increased 2- to 3-fold in arsenic-induced HCC and nontumorous, normal liver from arsenic exposed mice, while the tumor suppressors BRCA1 and BRCA2 decreased 30–50%." (PMID 16507464, 2006). "Tumours of BRCA1 and BRCA2 carriers aged 50 years or more differed significantly from those of younger carriers." (PMID 15987451, 2005). "The erbB2 results were very similar in the three groups of familial cases, with 18.6%, 15.1% and 17.4% of the BRCA1, BRCA2 and non-BRCA1/2 tumours, respectively, expressing the erbB2 antigen." (PMID 15642173, 2005). "Most of the earlier studies of the characteristics of tumours in BRCA1 and BRCA2 carriers have been based on young patients only." (PMID 15987451, 2005). "Furthermore, tumours from the older BRCA2 carriers exhibited distinctly different characteristics from the younger ones or from BRCA1 carrier tumours and mutation-negative ones, suggesting a strong impact of the germline mutation on tumour development among the older patients." (PMID 15987451, 2005). "The frequency of grade I and II tumours was much higher among the non-BRCA1/2 group than in the unselected control group (odds ratio 1.8, P = 0.009) or in the BRCA1 and BRCA2 groups." (PMID 15642173, 2005). "The clinical implication of these findings is still limited; however, it hints at differences in molecular mechanisms involved in tumour development in BRCA1 and BRCA2 carriers." (PMID 15138485, 2004). "The frequency of promoter hypermethylation of the tumor suppressor gene loci included in the panel was FHIT 28%, FANCF 24%, Cyclin-D2 12%, BRCA2 4%, and RUNX3 56% of the 25 tumours." (PMID 15574200, 2004). "This difference in the pattern of incidence rates is mirrored in the very different histopathology of tumours in BRCA1 and BRCA2 carriers, and reflects important mechanistic differences." (PMID 11857015, 2002). "LOH was found in the RAD51 region in 32% of tumours, in the RAD52 region in 16%, in RAD54 in 20% and in the BRCA1 and BRCA2 regions in 49% and 44% respectively." (PMID 10507777, 1999). "Multiple small molecules have been reported that inhibit HR by directly blocking RAD51 activity or disrupting its interaction with BRCA2, thereby preventing RAD51 filament assembly and inducing synthetic‐lethal cell death in tumours with heightened dependence on HR." (PMID 41537447, 2026).
tumor (continued). "Deficient HRR, primarily due to BRCA1/BRCA2 mutations, non-BRCA HRR gene alterations, and epigenetic changes, influences tumor behavior and enhances sensitivity to platinum-based chemotherapy and PARPi." (PMID 40864792, 2025). "Case 2 resulted in three out of the five analyzed tumor samples with the genetic profiles of premenopausal HER2(−)/ER(+)/PR(+), post-menopausal HER2(−)/ER(+)/PR(+) and pre-menopausal TNBC having the top ranked epitope for MHC class I as BRCA2." (PMID 41471728, 2025). "Furthermore, differences in tumor biology and systemic therapy response between BRCA1 and BRCA2 carriers require individualized strategies." (PMID 41302125, 2025). "PDX474.7, one of the selected models, was the most resistant of the whole cohort and displayed a BRCA2 mutation, whereas the other one, PDX252, was a BRCA1 mutant, where olaparib slows down tumor growth without achieving disease control." (PMID 41273720, 2025). "The link between BRCA2, PCMC, and breast malignancy remains to be fully elucidated." (PMID 40225096, 2025). "Biallelic germline BRCA2 truncating mutations were found in one familial case (WYE), where 2/3 children developed WT, but there was no tumor material to analyze somatic alterations." (PMID 40340749, 2025). "This could become even more important if guidelines are modified to include additional tumor types for which PARP inhibitors could be effective based on BRCA1 and BRCA2 status." (PMID 40853717, 2025). "Similarly, BRCA2 mutant tumor lines PEO1 and CAPAN1 also showed an increase in AP sites after cisplatin and HU treatment, compared to their BRCA2 restored counterparts, PEOC4 and C2-12, respectively." (PMID 41162355, 2025). "The breast cancer tumor-suppressor proteins BRCA1 and BRCA2 are important for DSB repair by homologous recombination (HR), and their dysfunction (deficiency) was shown to sensitize cells to PARP inhibition, resulting in chromosomal instability, cell cycle arrest, and subsequent apoptosis." (PMID 39684238, 2024). "We previously reported that none of the PARPi-resistant BRCA2-deficient tumours restored RAD51 IRIF12, whereas 64% (29/45) of the BRCA1-deficient tumours became RAD51 IRIF+." (PMID 38789420, 2024). "In particular, most BRCA1-related MBCs are grade 3, HER2-negative (HER2-) tumours with high proliferative activity, whereas BRCA2-associated MBCs are high-grade, HER2-positive (HER2+) tumours and show absence of progesterone receptor (PR) expression." (PMID 38974244, 2024). "For BRCA2 HomDels, selection for rare subclones without BRCA2-HomDel is observed following PARPi, confirmed by single circulating-tumor-cell genomics, biopsy fluorescence in situ hybridization (FISH), and RNAish." (PMID 39577422, 2024).
tumor (continued). "BRCA1/2 tumor NGS analyses were performed for 502 patients (50.3%), and a total of 62 TPVs were detected (12.4% of all NGS analyses); 31 TPVs in BRCA1 and 31 TPVs in BRCA2." (PMID 38730634, 2024). "A report on 1211 men with PCa who were undergoing active surveillance, including 11, 11, and 5 with BRCA1, BRCA2, and ATM germline carriers, respectively, revealed that BRCA2 carriers are more likely to undergo a tumor grade re-classification in subsequent biopsies." (PMID 39770431, 2024). "Panel sequencing of HRR-related genes additionally identified 1 tumor with a likely BRCA1 PV with gsLOH, 2 with BRCA2 PVs with gsLOH, and 1 tumor with a PV in PALB2 without gsLOH." (PMID 38648056, 2024). "The most common tumor types were ovarian (n = 23), breast (n = 15), pancreatic (n = 14), and prostate (n = 14); the most frequent enrollment genes were ATM (n = 38), BRCA1 (n = 28), BRCA2 (n = 15), SETD2 (n = 10), and CDK12 (n = 7)." (PMID 38710487, 2024). "The combined treatment increased the number of cytotoxic CD8+ T cells in the 2F8c model whereas no significant changes were found in the ID8p53–/– Brca2–/– tumor model." (PMID 39312740, 2024). "In the PROfound trial, a crossover randomized phase III trial, patients with mCRPC with BRCA1, BRCA2, and ATM tumor alterations showed improved survival when treated first-line with olaparib compared to enzalutamide or abiraterone (19.1 months vs. 14.7 months, HR = 0.69; p = 0.02)." (PMID 38927984, 2024). "But this possibility is called into question by the fact that genetically engineered Brca2 heterozygous mice are not tumor prone." (PMID 38271119, 2024). "The tumor suppressor genes BRCA1 and BRCA2 also play an important role." (PMID 37760950, 2023). "One tumor, with a negative GI status by Myriad MyChoice, had four ATM loss-of-function variants and a pathogenic BRCA2 variant." (PMID 38067228, 2023). "There was a significant difference in tumor morphology between BRCA1 and BRCA2 tumors (p < 0.001)." (PMID 36905492, 2023). "Based on these results, we concluded that the synthetic lethality by which POLQ and BRCA2 suppress tumor cells is a distinct mechanism independent of cGAS and STING." (PMID 36976649, 2023). "BRCA1, BRCA2, ATM, PALB2, and BAP1 were the DNA damage response GA found in our tumor samples." (PMID 36831055, 2023). "However, tumor cells with other mechanisms of PARPi resistance, such as BRCA1 or BRCA2 restoration, remain resistant to Polθ inhibitors." (PMID 36652375, 2023). "In 2005, two studies showed that the inhibition of PARP1 activity is specifically cytotoxic in cells lacking functional forms of the tumor suppressors BRCA1 or BRCA2." (PMID 37509303, 2023). "Analysis of the research set of samples, consisting of pairs of normal and tumor breast tissues from unselected patients, allowed us to find all the physiological mRNA junctions for the BRCA1 and BRCA2 genes that were previously identified in the validation set." (PMID 37046838, 2023). "In addition, FOXM1 is an upstream regulator of various DNA damage repair genes such as XRCC1, BRCA2, RAD51, BRIP1 and NBS1, thereby enabling the tumor cells to resist the action of the genotoxic agents." (PMID 37025658, 2023). "Therefore, we next tested the inhibitory effects of thioparib in a panel of tumor cell lines harboring BRCA1−/−, BRCA2−/−, PTEN−/−, or EWS‐FLI1 gene fusion." (PMID 36652375, 2023). "The three germline BRCA1/2 pathogenic variants not detected in tumour DNA were all large rearrangements and included two BRCA1 Exon 13 duplications (n = 2) and a BRCA2 Exon 1–24 deletion (n = 1)." (PMID 38201604, 2023). "Exploiting this vulnerability, PARPi selectively target tumor cells lacking functional BRCA1 or BRCA2." (PMID 37958290, 2023).
tumor (continued). "For instance, studies have revealed that tumor cells lacking BRCA1 or BRCA2 genes exhibit sensitivity to PARP inhibitors, suggesting a potential treatment option for patients with these mutations." (PMID 37781203, 2023). "One patient had a VUS in both BRCA2 and CHEK2 genes in her tumor." (PMID 37173992, 2023). "Anti-PD-L1 monotherapy improved the survival of mice with Brca1-null tumours, but not Brca2-null tumours." (PMID 38017453, 2023). "The last observation regarding tumor proliferation was also seen in patients with and without PGVs for BRCA2-tested PAM50 Luminal B cases (Mann–Whitney corrected p = 0.01, six tests)." (PMID 37060015, 2023). "Earlier studies have suggested that the survival of BRCA2 carrier patients does not vary by tumor grade, after other pathologic factors have been taken into account." (PMID 37173335, 2023). "The data showed an increase in TSPAN8 expression, but not THRSP expression, in BRCA2-mutant tumours compared with wild-type tumours." (PMID 37626143, 2023). "The panellists agreed that the choice of upfront treatment does not depend on the presence of a BRCA2 tumour (L)PV in both de novo low-volume and high-volume disease." (PMID 36874601, 2023). "Patients whose tumours had low levels of expression of BRCA2 with high levels of MRE11 co-expression had worse PFS (p = 0.005) and overall survival (p = 0.001) compared to patients whose tumours had high levels of BRCA2 with low levels of MRE11 co-expression." (PMID 37446144, 2023). "Costs for patients treated with olaparib, enzalutamide, or abiraterone increased substantially in the subgroup of patients with a tumor harboring at least one of three prespecified gene alterations (BRCA1, BRCA2, or ATM) versus those with at least one of 15 prespecified gene alterations." (PMID 37829336, 2023). "Tumor grade 3 predicted superior survival compared with grade 1 in BRCA2 carriers and young non-carriers, in contrast with the over threefold risk of death associated with grade 3 that was seen in the older group." (PMID 38036573, 2023). "Neither BRCA2 carriers nor young non-carriers did tumor grade 3 predict worse survival than did tumor grade 1." (PMID 38036573, 2023). "Since blocked replication forks cannot be restarted without the help of PARP1/2, SSB inevitably lead to more severe DSB; hence, tumor cells lacking active BRCA1 or BRCA2 are sensitive to a PARP inhibitor molecule." (PMID 37569269, 2023). "BC is further classified into several subclasses, characterized by immunohistochemical staining {(e.g., ER, PR, HER2 (ERBB2)}, proliferation marker protein Ki-67 (MKI67), genomic markers (e.g., BRCA1, BRCA2, and PIK3CA), and immunomarkers (e.g., tumor-infiltrating lymphocytes and PD-L1)." (PMID 36232989, 2022). "As the tumor progressed rapidly, genetic testing of tumor showed no mutation in BRCA1 and BRCA2 while UGT1AI*6, UGT1A1*28, UGT1A1-3156 gene polymorphism was detected." (PMID 36741732, 2022). "Intriguingly, in the other 50% of EP tumours, BRCA2 staining was either weak or completely absent (SI = 0 or 1)." (PMID 34045664, 2022). "Apart from RAD51C, none of the high HRD tumours harboured biallelic loss of other known HRD drivers, such as BRCA1 or BRCA2." (PMID 35039523, 2022). "Ligands that bind and stabilise G‐quadruplexes (G4s) have recently emerged as a class of compounds that selectively eliminate the cells and tumours lacking BRCA1 or BRCA2." (PMID 35107878, 2022).
tumor (continued). "We did not observe any clustering associated with tumor origin (breast or ovarian), tumor type (primary or recurrent), or germline mutation (BRCA1 vs. BRCA2)." (PMID 36344544, 2022). "In 2005, two studies revealed that tumor cells lacking BRCA1 or BRCA2 proteins are selectively vulnerable to PARPi." (PMID 35203410, 2022). "For example, in the PROfound trial, 145 patients with a tumor BRCA2 alteration were randomized while no patients with a tumor FANCL or RAD51C alteration were randomized." (PMID 35768576, 2022). "Among the 74 tumor samples harboring VUS only, 36 (48.6%) cases had alterations in BRCA1, 37 (50%) tumors had VUS in BRCA2 and one case (1.4%) presented VUS in both BRCA1 and BRCA2 genes." (PMID 35406410, 2022). "However, we found that the percent of (tumor and stromal) RAD51+ cells trended higher in tumors expressing BRCA2-001/Short compared to those expressing BRCA2-201/Long." (PMID 36344544, 2022). "The first analysis of the IMPACT trial concluded that patients with BRCA2 PVs have elevated levels of serum prostate specific antigen (PSA) at diagnosis, predominantly high Gleason tumours, increased rates of nodal and distant metastases, and finally high recurrence rates." (PMID 36010882, 2022). "Because homologous recombination (HR) repair is abrogated in the absence of BRCA1 or BRCA2, these lesions are specifically lethal to tumour cells, but not to the healthy tissue." (PMID 35107878, 2022). "We show that xenograft tumours lacking BRCA1 or BRCA2 are hypersensitive to pyridostatin and that the in vivo activity of this compound is similar to that of the PARPi talazoparib." (PMID 35107878, 2022). "In 2005, two groundbreaking studies observed that tumor cells lacking BRCA1 or BRCA2 were particularly sensitive to PARPi through various mechanisms." (PMID 35740616, 2022). "The other tumor (M232) only showed LOH at the BRCA1 and BRCA2 loci without loss of function in the other allele." (PMID 35662281, 2022). "High expression levels of AKT1 (p = 0.01), IFNGR1 (p = 0.01), and BRCA2 (p = 0.02) were predictive of early trabectedin treatment failure, irrespective of tumor grade." (PMID 35267598, 2022). "In accordance with this, BRCA2 protein expression was weak or completely absent in around 50% of the tested EP tumour samples." (PMID 34045664, 2022). "In our series, one patient previously found to be a carrier of a germline BRCA2 PV was negative at tumour testing, likely since it was located in a homopolymeric region, which is usually inefficiently sequenced by Ion torrent-based techniques." (PMID 35463374, 2022). "The group with OvCa and with no tumor were significantly different (p < 0.001 and p < 0.01, respectively), with an older age for the BRCA2 gene, consistent with the reported data." (PMID 34072659, 2021). "Two tumor suppressor genes, BRCA-1 and BRCA-2, play a role in DNA repair." (PMID 34660022, 2021). "Cyclin D1 overexpression specifically decreased the proliferation of cells lacking BRCA1 or BRCA2, consistent with the mutual exclusivity of BRCA1/2 mutations and CCND1 amplification in tumours." (PMID 34389725, 2021). "Tumours from women who tested BRCA PV negative in the high-risk cohort were more likely to be grade 1 than both BRCA1 (p < 0.001) and BRCA2 (p = 0.04) tumours." (PMID 34312777, 2021). "The second tumor, PS13-1760, was classified as a grade 3 node negative ER+ PR− ERBB2+ (3+) (pT2, pN0) and had a somatic BRCA2 mutation." (PMID 34011996, 2021).